CDC42 (cell division cycle 42)
Diseases named in the same sentence as CDC42 in open-access papers (continued):
Sharing a sentence is not in itself a finding about the gene and the disease.
Takenouchi-Kosaki syndrome (11 papers, 2019 to 2024). "Pathogenic variants in RAC1 cause the autosomal dominant inherited intellectual developmental disorder type 48 (OMIM # 617751), while heterozygous pathogenic variants in CDC42 can cause Takenouchi-Kosaki syndrome (OMIM # 616737)." (PMID 38501224, 2024). "Mutations in the CDC42 gene are associated with Takenouchi-Kosaki syndrome, in which some patients develop sensorineural hearing loss." (PMID 35573665, 2022). "First reported case of Takenouchi-Kosaki syndrome in an African patient with a de novo likely pathogenic missense variant identified in the CDC42 gene." (PMID 33936654, 2021). "The present results suggest that the mechanistic basis of macrothrombocytopenia in Takenouchi-Kosaki syndrome involves a hypomorphic effect exerted by the p.Tyr64Cys mutation in CDC42." (PMID 30872706, 2019). "Intriguingly, the partial phenotype observed in our patients—including intellectual disability, hearing loss, facial dysmorphism, and camptodactyly—significantly overlaps with those seen in a patient with Takenouchi-Kosaki syndrome and a heterozygous c.191A>G (p.Tyr64Cys) variant in CDC42." (PMID 40225942, 2024). "Furthermore, heterozygous CDC42 missense variants have been related to the Takenouchi-Kosaki syndrome (TKS)." (PMID 33488606, 2020). "In the patient studied, a syndromic phenotype with facial dysmorphism, neurodevelopmental delay, immunodeficiency, autoinflammation, and hemophagocytic lymphohistiocytosis shares common features with Takenouchi-Kosaki syndrome and with C-terminal variants in CDC42." (PMID 32231661, 2020). "The identification of multiple unrelated patients with similar phenotypes and exactly the same de novo CDC42 mutation enabled us to confirm that these patients represent a new syndromic form of thrombocytopenia, which was eponymized as “Takenouchi-Kosaki syndrome” (OMIM #616737)." (PMID 30872706, 2019). "The combined phenotype of thrombocytopenia accompanied by intellectual disability in patients with a de novo heterozygous mutation, i.e., p.Tyr64Cys in CDC42, signifies a clinically recognizable novel syndrome that has been eponymized as “Takenouchi-Kosaki syndrome” (OMIM #616737)." (PMID 30872706, 2019). "We also suggst that feeding disorders, malnutrition, and a gastrointestinal infection could be a part of the phenotypic characteristics of Takenouchi-Kosaki syndrome supporting the hypothesis of immune dysregulation and systemic inflammation occurring in the p.Tyr64Cys variant in CDC42." (PMID 37347054, 2023). "Many de novo mutations within the CDC42 gene result in heterogeneous phenotypes with highly variable symptoms including facial dysmorphism, dysregulation of growth, haematological as well as immunological and neurodevelopmental abnormalities such as Takenouchi-Kosaki syndrome (TKS)." (PMID 36699687, 2022). "Takenouchi-Kosaki syndrome (TKS) harboring the c.191A > G, Tyr64Cys (Y64C) variant in Cdc42 exhibits a variety of clinical manifestations, including immunological and hematological anomalies." (PMID 34504210, 2021). "In the present study, we sought to delineate the pathogenetic basis of the macrothrombocytopenia observed in Takenouchi-Kosaki syndrome and performed a functional analysis of p.Tyr64Cys in cdc-42 using CRISPR/Cas9-mediated gene editing and Caenorhabditis elegans." (PMID 30872706, 2019). "Heterozygous missense variants in CDC42 have recently been associated with a heterogeneous developmental disorder that includes variable growth dysregulation, facial dysmorphism, and neurodevelopmental, immunological, and hematological abnormalities (MIM: 616737, Takenouchi-Kosaki syndrome)." (PMID 34022130, 2021).
nasopharyngeal carcinoma (10 papers, 2012 to 2025). A carcinoma arising from the nasopharyngeal epithelium. "miR-204-5p acts through cdc42 to aid the invasion of EBV-associated nasopharyngeal carcinoma cells." (PMID 33790326, 2021). "What’s more, it was reported that HMGB1-RAGE signalling triggered activation of several key cell signalling pathways, such as MAPK, NF-κB, and Rac/Cdc42 in nasopharyngeal carcinoma." (PMID 34933679, 2021). "It seems that FGD4 is also involved in the tumorigenesis of nasopharyngeal carcinoma due to its activation of CDC42." (PMID 32772928, 2020). "One study showed that the latent membrane protein (LMP) 1 of Epstein-Barr virus promotes increased motility of nasopharyngeal carcinoma (NPC) cells through increased CDC42 activity and remodeling of the actin cytoskeleton." (PMID 30558664, 2018). "In nasopharyngeal cancer cells, Cdc42 modulates PKC-ζ expression to control telomerase activity." (PMID 36077689, 2022). "FGD2, for instance, activates CDC42 and has an important paralog, FGD4, which has been found to interact with EBV LMP1 protein to activate CDC42, a mechanism suggested to be implicated in the nasopharyngeal carcinoma tumurogenesis." (PMID 28654678, 2017).
COVID-19 (9 papers, 2021 to 2024). A disease caused by infection with severe acute respiratory syndrome coronavirus 2. "Building upon the observed relationship between Cdc42 and cellular senescence, our study aimed to explore the potential of targeting Cdc42 as a therapeutic and preventive approach for COVID-19 and its associated complications." (PMID 39559701, 2024). "COVID-19 patients showed alterations in KPNA3, KPNA5, KPNA7, KPNB1, RHOA, and CDC42 expression compared with non-COVID-19 patients." (PMID 34696514, 2021). "miR-185 also seems to be associated with infectious diseases, being one of the top ten most important downregulated miRNAs as possible biomarkers of severity of COVID-19, and shows anti-inflammatory functions through inhibiting CDC42, which has a pro-inflammatory role." (PMID 38872198, 2024). "All three Rho GTPases, RHOA, CDC42, and RAC1, showed a significant decrease in gene expression upon age in COVID-19 patients (p-trend decreasing = 0.002, p-trend decreasing = 0.008, p-trend decreasing = 0.004, respectively)." (PMID 34696514, 2021). "In conclusion, our study provides global insights into the transcriptome profiles of host responses in COVID-19-vaccinated individuals and identifies MAPK1, CDC42, PPP2CA, EP300, YWHAZ and NRAS as hub genes that are significantly correlated with the vaccine response." (PMID 37096063, 2023). "Results show that RHOA and CDC42 expression was significantly decreased (p = 0.0036, p = 0.0044, respectively) in COVID-19 compared with non-COVID-19 patients (B.I)." (PMID 34696514, 2021).
Ewing sarcoma (9 papers, 2010 to 2025). A small round cell tumor that lacks morphologic, immunohistochemical, and electron microscopic evidence of neuroectodermal differentiation. "We demonstrate that a USP1 inhibitor, ML323, is able to activate cdc42 and inhibit growth in Ewing sarcoma." (PMID 38323120, 2024). "The oncogenic function of CDC42 in Ewing sarcoma is further supported by a study demonstrating that CDC42 activation and upregulation is partly responsible for the role of hepatoma-derived growth factor (HDGF) in local invasion." (PMID 36594908, 2021). "A pharmacological inhibitor of USP1 was able to activate cdc42 and inhibit Ewing sarcoma growth." (PMID 38323120, 2024). "Also, in the pathogenesis of Ewing Sarcoma, a highly aggressive bone tumour, miR‐130b was reported to induce proliferation, invasion, and migration in vitro and increase metastatic potential via activation of the Cdc42 and Pak1 pathway." (PMID 32860492, 2020). "We also find that USP1 inhibits cdc42, increases EWS-FLI1 transcriptional output, and simulates Ewing sarcoma growth." (PMID 38323120, 2024). "We also found that USP1 inhibits cdc42, enhances EWS-FLI1 transcriptional output, and stimulates Ewing sarcoma growth." (PMID 38323120, 2024). "In addition, we found that non-treated Ewing's sarcoma cell lines showed almost no activation of cdc42 and cdc42 was not activated upon bFGF stimulation (data not shown)." (PMID 20606682, 2010).
triple-negative breast carcinoma (9 papers, 2017 to 2025). An invasive breast carcinoma which is negative for expression of estrogen receptor (ER), progesterone receptor (PR), and human epidermal growth factor receptor 2 (HER2). "On the one hand, high levels of NRBP1 have been shown to enhance proliferation and metastasis in bladder cancer, as well as influence the oncogenic potential of triple-negative breast cancer cells via the P-Rex1/Rac1/Cdc42 pathway." (PMID 41430038, 2025). "Specifically, we determined CDC42 expression levels in human MDA-MB-231 triple-negative breast cancer cells before and after metformin exposure and observed a striking down regulation of CDC42 expression in the presence of metformin." (PMID 28423712, 2017). "ERK3 knockdown significantly decreased the levels of both basal and EGF-induced GTP-bound CDC42 and RAC1 in primary (HMEC) and triple-negative breast cancer (MDA-MB231) mammary epithelial cells, respectively." (PMID 37057894, 2023). "For example, TRIP10 downstream effector of CDC42 is hyperphosphorylated in non-responder cohorts and in triple negative breast cancer, the hypermethylation of TRIP10 is related with the prediction of response to neoadjuvant chemotherapy." (PMID 36393868, 2022). "Here we demonstrated that DAPT, a gamma secretase inhibitor, inhibited protrusion formation and cell motility, and then reduced the migration of triple-negative breast cancer cells, through increasing the activity of Cdc42 by non-canonical Notch pathway." (PMID 31057403, 2019).
bladder cancer (8 papers, 2021 to 2025). "Loss or dominant-negative of Cdc42 has been reported to be associated with increased apoptosis in several cell types, including podocytes, human T-cells, and bladder cancer cells." (PMID 38139048, 2023). "It has been reported that silencing CDC42 significantly promoted apoptosis and inhibited proliferation in bladder cancer cell." (PMID 41169985, 2025). "We demonstrated that hAM homogenate significantly decreased the expression of Cdc42 and Rac1/2/3 in bladder cancer urothelial T24 and RT4 cells." (PMID 37932474, 2023). "Our study showed that hAM homogenate strongly reduced the expression of Cdc42 and Rac1/2/3 in non-invasive and invasive bladder cancer urothelial cells, while hAM extract had no inhibitory effect." (PMID 37932474, 2023). "Expression levels of IQGAP3 in tissue and urine samples from bladder cancer patients are significantly higher than those in samples from control groups, and IQGAP3 was upregulated by CDC42 activation of the Ras/ERK pathway, promoting the development of bladder cancer." (PMID 36362301, 2022). "In this study, we found that cell movement is RAC1-dependent in bladder cancer, and RAC1 activity, but not RhoA and CDC42, is inhibited by RACGAP1, which is partially reversed following SHCBP1 ectopic expression." (PMID 35013128, 2022).
diabetic nephropathy (8 papers, 2012 to 2024). "Of further relevance to our finding, Cdc42 is implicated in insulin secretion and is linked to insulin resistance and diabetic nephropathy." (PMID 37365285, 2023). "A recent transcriptome analysis of human diabetic kidney disease pointed towards CDC42 signaling as an important dysregulated pathway, which is in accordance with the presence of CDC42 as an important hub in the network we present here." (PMID 22340758, 2012). "Cdc42 was highly expressed in the podocytes of diabetic nephropathy mice." (PMID 36034435, 2022). "The Rho family member Cdc42 was also found uniquely to be activated in cells treated with TGFβ and CCN2; Cdc42 interacting genes were differentially regulated in diabetic nephropathy." (PMID 23902294, 2013).
Intellectual disability (8 papers, 2013 to 2024). "Recently, we reported two unrelated individuals with thrombocytopenia accompanied by intellectual disability and a de novo mutation in CDC42, a critical molecule in the regulation of the cell cycle and the formation of the actin cytoskeleton." (PMID 30872706, 2019). "Dysfunctional Rac1/Cdc42 has been associated with aberrant synaptic plasticity and intellectual disability." (PMID 31379509, 2019). "A total of five patients with macrothrombocytopenia, intellectual disability, and a de novo heterozygous mutation in CDC42, i.e., p.Tyr64Cys, have been identified." (PMID 30872706, 2019). "Misregulated RhoA, Rac1/Rac3 and cdc42 activity has been linked with intellectual disability (ID) and other neurodevelopmental conditions that comprise ID." (PMID 29925821, 2018). "Dysregulation of MEGAP, another RhoGAP for Rac1 and Cdc42, has also been associated with intellectual disability and microcephaly." (PMID 27795858, 2016). "Mutation in oligopherinin 1, a RhoGAP for RhoA, Rac1, and Cdc42, leads to reduction in spine length and number of mature spines accompanied by resulting phenotypes including intellectual disability, epilepsy, microcephaly, ataxia, and hyperactivity." (PMID 27795858, 2016). "The phenotypic features of TKS related to the p.Tyr64Cys variant in CDC42 comprise psychomotor developmental delay, intellectual disability, dysmorphism, sensorineural hearing loss, cardiac and genitourinary malformations, and macrothrombocytopenia, consistent also with the herein reported patient." (PMID 37347054, 2023). "For example, human orthologs to fly genes CASK (CASK), Mnb (DYRK1A), Dlg-1 (DLG1), Cdc42 (CDC42), Fmr1 (FMR1, FXR1/2), trio (TRIO), Nedd4 (NEDD4L/NEDD4) and CamKII (CAMK2A/B/D) have been linked to intellectual disability." (PMID 37759179, 2023).
non-small cell lung carcinoma (8 papers, 2015 to 2024). A group of at least three distinct histological types of lung cancer, including non-small cell squamous cell carcinoma, adenocarcinoma, and large cell carcinoma. "Therapies targeting CDC42-dependent pathways are being explored as treatments for cancers with high mortality such as non-small cell lung cancer." (PMID 35514537, 2022). "In a study on human non-small cell lung cancer, miR-29a overexpression led to significant inhibition of Cdc42 protein expression, whereas Cdc42 mRNA expression was unchanged." (PMID 31662747, 2019). "Here, we investigated the clinical significance of GIT1 expression in non-small-cell lung cancer (NSCLC) and also verified the importance of GIT1-Rac1/Cdc42 axis in stimulating NSCLC cell mobility." (PMID 26462147, 2015).
Obesity (8 papers, 2016 to 2025). Accumulation of substantial excess body fat. "The association between increased Cdc42 activity and inhibition of autophagy in hepatocytes sheds light on potential mechanisms underlying obesity-related insulin resistance." (PMID 38068822, 2023). "This review explores the complex relationships among age-associated obesity, the insulin–leptin axis, and the Cdc42 signaling pathway." (PMID 38068822, 2023). "Specific deletion of ROCK1, a downstream kinase of the CD44/ankyrin/Cdc42 signaling pathway, attenuated obesity-associated insulin resistance in adipose tissue, indicating a role in obesity-related metabolic syndromes." (PMID 37894408, 2023). "In the pancreas of C57BL/6 mice, obesity caused a decrease in Cdc42 expression, especially in four-week-old animals, whereas older animals showed a slight reduction." (PMID 38068822, 2023). "Considering the close relationships between obesity, leptin resistance, insulin resistance, and aging, it is conceivable that Cdc42 dysfunction may be associated with leptin resistance." (PMID 38068822, 2023). "Importantly, Cdc42 plays a vital role in cellular processes associated with the insulin and leptin signaling pathways, which are integral elements involved in obesity development if misregulated." (PMID 38068822, 2023). "Potential interventions targeting Cdc42 activity hold promise for reducing obesity and enhancing leptin sensitivity." (PMID 38068822, 2023). "It is noteworthy to mention that some drugs used to sensitize tissues to leptin and affect obesity can modulate Cdc42 activity." (PMID 38068822, 2023). "Aging exacerbates obesity-induced vascular pathology, whereas activation of Cdc42 regulates vascular function positively in young organisms." (PMID 38068822, 2023). "Upregulation of Cdc42 in obesity contributes to the development of insulin resistance through increased leptin production by hypertrophied adipocytes." (PMID 38068822, 2023). "A mouse transcriptome study showed that obesity modulates Cdc42 expression in different mouse organs in an age-dependent manner." (PMID 38068822, 2023). "One reason for the increase in Cdc42 activity may be related to the change in adipocyte size, which is affected by age and obesity: average adipocyte size increases in middle and old age and then decreases over time." (PMID 38068822, 2023). "Thus, it is evident that obesity mostly has an increased impact on Cdc42’s ability to operate in a variety of tissues." (PMID 38068822, 2023). "Since increased Cdc42 and MMP-2 activity are observed in obesity and aging, it is conceivable that increased Cdc42 activity may lead to the degradation of the leptin receptor and affect leptin transport to the brain." (PMID 38068822, 2023). "In addition, this article discusses the potential therapeutic implications of the Cdc42 pathway to mitigate obesity." (PMID 38068822, 2023). "Although we have not found any studies on the effect of selective Cdc42 inhibitors on obesity, it has been shown that systemic administration of a selective small molecule, the Cdc42 inhibitor CASIN, can significantly reduce inflammatory processes in the body and increase life expectancy." (PMID 38068822, 2023). "Therefore, it could be of great interest to evaluate the effects of Cdc42 inhibitors and activators on leptin resistance and obesity." (PMID 38068822, 2023). "In addition, it also discusses the potential therapeutic implications of the Cdc42 pathway to mitigate obesity since some new data suggest that inhibition of Cdc42 using antidiabetic drugs or antioxidants may promote weight loss in overweight or obese patients." (PMID 38068822, 2023). "Overall, PRK-CA, EGFR, CDC42, and VEGF-A were found to be upregulated in this study and imply a role of focal adhesion in NAFLD development and obesity." (PMID 31771247, 2019). "In the BTBR mice groups, the induction of Cdc42 in the liver during obesity was independent of age but was less pronounced than in C57BL/6 mice." (PMID 38068822, 2023).
Obesity (continued). "Increased expression of Cdc42 was also observed in obese livers, with the most significant changes observed in the obese C57BL/6 mice group at ten weeks of age, whereas in mice of the same line at four weeks of age, Cdc42 levels were unchanged in obesity." (PMID 38068822, 2023). "In the hypothalamus of mice, obesity and age did not lead to changes in Cdc42 expression." (PMID 38068822, 2023).
osteosarcoma (8 papers, 2005 to 2025). A usually aggressive malignant bone-forming mesenchymal neoplasm, predominantly affecting adolescents and young adults. "PAK7, a member of the p21-activated kinase family, promotes cell invasion in gastric and osteosarcoma contexts via the Rac1/Cdc42 pathway." (PMID 41153973, 2025). "We evaluated the activations of RhoA, Rac1 and Cdc42 in osteosarcoma MG-63 and U2OS cells with small G-protein activation assay." (PMID 28289332, 2017). "To summarize, we have identified the Rac1- and Cdc42-specific GAP, cdGAP as a key mediator of FA based mechanosensing of the ECM and as an important regulator of durotaxis in U2OS osteosarcoma cells." (PMID 24632816, 2014).